PDGFRB (platelet derived growth factor receptor beta)
Diseases named in the same sentence as PDGFRB in open-access papers (continued):
Sharing a sentence is not in itself a finding about the gene and the disease.
tumor (continued). "We recommend testing of IM tumor tissue for the presence of PDGFRB mutations by next-generation sequencing (NGS)." (PMID 32888134, 2021). "In univariate analysis, we showed that there was an association between high tumor cell PDGFRB expression and shorter survival." (PMID 33955203, 2021). "In this study, we have shown that high FAP and SPARC expression in tumor stroma and high PDGFRB expression in tumor cells are associated with shorter survival in MPM patients in univariate analysis." (PMID 33955203, 2021). "In univariate Cox regression, higher PDGFRB expression in MPM tumor cells was associated with shorter survival in MPM patients (HR = 1.02, p < 0.001, corrected P value = 0.04)." (PMID 33955203, 2021). "In external validation, high tumor cell PDGFRB expression associated with shorter survival, especially in the epithelioid subtype." (PMID 33955203, 2021). "To determine the mechanisms associated with inhibition of tumor progression by Pdgfrβ and Pkcα inhibitors, we analyzed Brca1-deficient tumors by western blot." (PMID 33478572, 2021). "In univariate Cox regression analysis, high relative tumor PDGFRB area was associated with shorter survival (HR = 2.10, p = 0.010, corrected P value = 0.041) in an independent validation cohort." (PMID 33955203, 2021). "To determine the role of Pdgrfβ in Brca1-deficient tumorigenesis, we knocked out Pdgfrβ in p18−/−;Brca1MGKO primary tumor cells by using the CRISPR/Cas9 system." (PMID 33478572, 2021). "This study not only reveals the molecular mechanism of BRCA1 in suppressing EMT but also tests the efficacy of inhibitors that target PDGFRβ-PKCα signaling on suppressing BRCA1-deficient tumor initiation and progression." (PMID 33478572, 2021). "Recently, we found increased levels of THBS4, an ECM protein, is highly associated with PDGFRβ expression in tumor tissues when compared to normal tissues of colon cancer patients." (PMID 34502094, 2021). "Univariate Cox regression showed that higher tumor cell PDGFRB associated with shorter survival with an HR of 4.48 (95% CI = 1.34–14.99; p = 0.015)." (PMID 33955203, 2021). "In the epithelioid subtype, PDGFRB expression was associated with solid or micropapillary tumor architecture." (PMID 33955203, 2021). "Recently, it was found that there are increased levels of THBS4 in colorectal cancer patients and it is highly associated with PDGFRβ expression in tumor tissues compared to normal tissues." (PMID 34502094, 2021). "Consistently, pharmaceutical inhibition of Pdgfrβ or Pkcα activity suppressed Brca1-deficient tumor initiation and progression." (PMID 33478572, 2021). "Of the investigated fibroblast markers, high expression of FAP and SPARC in tumor stroma and high expression of PDGFRB in MPM tumor cells were associated with shorter survival." (PMID 33955203, 2021). "Targeted deletion of Pdgfrβ in Brca1-deficient tumor cells inactivated Pdgfrβ-Pkcα signaling, promoted cell death, induced MET, and suppressed tumorigenesis." (PMID 33478572, 2021). "In particular, given that pharmaceutical inhibition of PDGFRβ efficiently promotes cell death of BRCA1-deficient tumor cells, it indicates the potential to tailor specific therapies to BLBC patients with BRCA1 deficiency." (PMID 33478572, 2021). "Cancer-associated fibroblasts have been implicated in tumor radioresistance and can be identified by platelet-derived growth factor receptor-beta (PDGFRb)." (PMID 33661437, 2021). "This is consistent with the data derived from targeted deletion of Pdgfrβ, and these results further confirm that inhibition of Pdgfrβ-Pkcα signaling promotes Brca1-deficient tumor cell death and MET." (PMID 33478572, 2021). "Confirming this role, targeted deletion of Pdgfrβ in Brca1-deficient tumor cells promoted cell death, induced mesenchymal-to-epithelial transition, and suppressed tumorigenesis." (PMID 33478572, 2021).
tumor (continued). "In conclusion, in the primary cohort of MPM patients including long‐term survivors, high FAP and SPARC expression in stromal cells and high PDGFRB expression in tumor cells were associated with shorter survival." (PMID 33955203, 2021). "Although malformed blood vessels often presented thick-wall and irregular shape, we found that most of the PDGFRβ+ cells within the tumor stroma remained associated with the vasculature." (PMID 34535655, 2021). "In conclusion, our work identified FAP/PDGFRβ dual positive tumor-associated pericytes as a distinct stromal cell type in the GBM tumor microenvironment." (PMID 33308315, 2020). "It is well known that overexpression of PDGFRβ on endothelial cells and tumor-associated stromal cells surface occurs in different human cancers, where the receptor establishes complex signaling pathways inducing angiogenesis and tumor progression." (PMID 32892748, 2020). "The following tumor mutations were reported in patients with clinical benefit: cKIT (n = 1), CSF-1R (n = 1), PDGFRα (n = 2), PDGFRβ (n = 1), VEGFR1 (n = 1), VEGFR2 (n = 2), FLT3 (n = 1), FGFR2 (n = 2), RET (n = 1), and TrkA (n = 1)." (PMID 32292573, 2020). "The overexpression of PDGFRβ has been associated with tumor progression features such as cell migration, metastasis, angiogenesis, and proliferation." (PMID 33374773, 2020). "Several patients experienced clinical benefit with tumor mutations in cKIT, CSF-1R, PDGFRα, PDGFRβ, VEGFR1, VEGFR2, FLT3, FGFR2, RET, and TrkA." (PMID 32292573, 2020). "Tumor mRNA level of PDGFRB was significantly associated with serum PDGF-BB (R = 0.395, p = 0.009) and marginal significance with serum PDGF-AA (p = 0.077)." (PMID 32235327, 2020). "The primary tumor sample with the D850V mutation in PDGFRB had concurrent mutations in PTCH1 (c.961C > A), ATR (c.4704C > G), and CDKN1A (c.419_420delGA)." (PMID 31480474, 2019). "Co-occurring alterations included a NOTCH2 copy number gain in the PDE4DIP-NOTCH2 fusion positive tumor and PDGFRB mutations in both fusion-positive cases." (PMID 31480474, 2019). "In our analysis of vascular lacunae, a trend of association was revealed between PDGFRβ in tumor cells in vascular-like structures and CDCP1 expression (p = 0.0795; Fisher’s exact test)." (PMID 29792166, 2018). "Further, our group has demonstrated that the ability of TNBCs to form vascular-like channels is associated with increased tumor aggressiveness and that this phenotype is related strictly to the expression of PDGFRβ." (PMID 29792166, 2018). "Because PDGFRβ affects multiple tumors associated with various processes, including the autocrine growth stimulation of tumor cells and tumorigenesis, it has been targeted for the development of anticancer therapy." (PMID 29991770, 2018). "To conclude, our work demonstrated that tumor cells with the c.1681C>T (p.R561C) mutation in PDGFRB show high levels of PDGFR-beta and ERK1/2 phosphorylation." (PMID 30200486, 2018). "Expression of PDGFB by cancer cells and that of PDGFRβ by tumor-associated stromal cells are strongly associated with lymphatic metastasis." (PMID 30018456, 2018). "It is well demonstrated that overexpression of PDGFRβ on endothelial cells and tumor-associated stromal cells occurs in different human cancers, where complex PDGFRβ-dependent signaling contributes to angiogenesis and tumor progression." (PMID 30428522, 2018). "Owing to the high expression of PDGFRβ in tumor-associated pericytes and the high affinity and specificity of ZPDGFRβ affibody for PDGFRβ, pericyte-targeted delivery can be achieved by the conjugation of PS to the ZPDGFRβ affibody." (PMID 29182023, 2017). "By analyzing the KEGG (Kyoto Encyclopedia of Genes and Genomes) pathway annotation in these data sets, we revealed that several pathways were significantly associated with PDGFRα and PDGFRβ expression, respectively, in the five separate tumor cohorts." (PMID 25576913, 2015).
tumor (continued). "Significant positive associations were observed between urinary PDGFRB levels and tumor size (P = 0.03) and age (P = 0.019)." (PMID 24801713, 2014). "Several intracellular and plasma membrane-associated proteins such as α-SMA, vimentin, and PDGFRβ have been used as CAF markers to detect CAFs in tumor tissue." (PMID 24734219, 2014). "Novel associations between TMPRSS2-ERG and alterations in the tumor stroma, for example, increased vascular density, hyaluronan and PDGFRβ and decreased Caveolin-1, all known to be associated with an aggressive disease, were found." (PMID 24505269, 2014). "A recent analysis has demonstrated significant associations between the PDGFRβ status in prostate carcinomas with histopathological tumor characteristics, such as Gleason score and tumor stage and clinical characteristics, including survival." (PMID 22791264, 2013). "Analysis at both the mRNA and protein level revealed that PDGFRα and PDGFRβ were consistently upregulated in tumor cells and tumor tissue following loss of IGF-IR expression." (PMID 22070644, 2011). "Whereas PDGFRβ expression is common on tumor-associated pericytes, its expression on tumor-associated ECs appears to be more restricted." (PMID 27713269, 2010). "The present analyses uncovered a set of novel associations between the tumor stroma PDGFRβ status and histopathological characteristics, including positive correlations with Gleason score, tumor stage and tumor size." (PMID 20505768, 2010). "High PDGFRβ expression in tumor stroma was associated with large tumor size, advanced stage, high Gleason score and high vessel density." (PMID 20505768, 2010). "In summary, signaling and functional assays in CRC cell lines showed that PDGF-BB–mediated PDGFRβ activation remodels the secretome of tumor-associated fibroblasts—especially by increasing the release of CCL5 and CXCL12—thereby promoting CRC cell proliferation and migration." (PMID 41601676, 2026). "Furthermore, epithelial-mesenchymal transition, inflammatory response, myogenesis, and TNFA signaling were significantly enriched, suggesting that high PDGFRB expression is linked to processes involved in tumor metastasis and immune regulation." (PMID 41376620, 2025). "Specifically, PDGFRα overexpression correlated with higher tumor grade and positive nodal status (pN+), while PDGFRβ overexpression was linked to the extent of tumor-associated thrombosis, the presence of distant metastases, and adrenal metastases (P < .05 for all correlations)." (PMID 40434293, 2025). "In addition to these studies above, mostly implying PDGFRβ as the key receptor, other studies have linked PDGFRα to tumor-restraining effects." (PMID 38980580, 2024). "Furthermore, patient outcomes were analyzed with respect to the integrin α11/PDGFRβ+ CAF subgroup, showing that an increase in stromal density of integrin α11/PDGFR was associated with higher tumor grade, metastasis, and patient mortality." (PMID 37496657, 2023). "PDGFRβ is the representative biomarker of tumor vessel–associated pericytes, and we also verified the good colocalization of PDGFRβ and blood vessel biomarker CD31 in the HCC tissues of monkey, indicating that PDGFRβ is a potential target for molecular imaging of vascularized tumors." (PMID 37256321, 2023). "The primary and PDX tumours had somatic mutations in PDGFRB (NM_002609: p.N666K)." (PMID 36522480, 2023). "PDGFRB signaling is implicated in covering new blood vessels with pericytes, providing their remodeling, stabilization, and maturation, as well as the regulation of vascular perfusion, contributing to tumor growth." (PMID 35406617, 2022). "Tumor cell PDGFRB and stromal SPARC expression in particular were associated with shorter survival and may play critical roles in the pathogenesis of MPM." (PMID 33955203, 2021). "High tumor cell PDGFRB and high stromal SPARC were independently associated with survival." (PMID 33955203, 2021).
tumor (continued). "Additionally, as an alternative model for investigating the role of perivascular cells in tumour revascularization, HT‐29 tumour‐bearing mice were treated with PDGFRβ neutralizing antibodies to deplete vessel‐associated PDGFRβ+ perivascular cells." (PMID 34035882, 2021). "Additionally, these data also indicate that activation of Pkcα and its downstream target Fra1 is dependent on Pdgfrβ signaling, and Pdgfrβ signaling is required for maintaining the mesenchymal traits in Brca1-deficient tumor cells." (PMID 33478572, 2021). "Nevertheless, ERK activation by PDGFRβ signaling pathway cannot compensate the loss of HIF1α-PDGFD-PDGFRα-AKT network for GBM tumor growth because knockout of either HIF1A or PDGFD or PDGFRA in U251 cells eradicated the tumor growth." (PMID 34470658, 2021). "As a whole, these data suggest that loss of Brca1 induces EMT and metastatic basal-like tumors in an epithelium-autonomous manner and that Brca1 loss activates Pdgfrβ-Pkcα signaling in epithelial tumor cells thereby enriching the number of tumor cells with EMT-like features." (PMID 33478572, 2021). "Importantly, we also found that pharmaceutical inhibition of Pdgfrβ and its downstream target Pkcα suppressed Brca1-deficient tumor initiation and progression and effectively killed BRCA1-deficient cancer cells." (PMID 33478572, 2021). "A multivariable survival analysis adjusted for clinical parameters and stromal mfIHC markers revealed that tumor cell PDGFRB and stromal SPARC remained independently associated with survival (HR = 1.01, 95% confidence interval [CI] = 1.00–1.03 and HR = 1.05, 95% CI = 1.00–1.11, respectively)." (PMID 33955203, 2021). "However, there was a positive association between unfavorable tumor architecture (predominantly solid or micropapillary growth pattern) and high tumor cell PDGFRB expression (p = 0.020)." (PMID 33955203, 2021). "Tumor development and progression are promoted by the establishment of a favorable TME, including PDGFRβ-positive mesenchymal stem cells (MSCs), tumor-associated fibroblasts, angiogenic endothelial cells, and infiltrating immune cells, through a cytokine network." (PMID 32892748, 2020). "PDGFRβ was used to mark tumor-associated pericytes in GL261 GBM." (PMID 33308315, 2020). "Therefore, we took the top 20 genes in Degree and the tumor-associated pathway-related gene to take Venn intersection, and identified three Hub genes: PDGFRB, KDR and FGF2." (PMID 32011476, 2020). "There is increasing evidence that THBS4 and PDGFRβ are associated with tumor development." (PMID 32899998, 2020). "Interestingly, co-occurring alterations included a NOTCH2 copy number gain in the PDE4DIP-NOTCH2 fusion tumor and PDGFRB mutations in both fusion-positive cases." (PMID 31480474, 2019). "In addition, PDGFRβ signalling promotes expression of IL-33 by pericytes, which recruits tumour-associated macrophages that promote tumour metastasis." (PMID 30097696, 2018). "Notably, expression of CD146, NG2, and PDGFRβ was somewhat reduced in the population of tumor-associated pericytes, in agreement with previous studies reporting variable expression of some of these markers in pathological conditions." (PMID 28553358, 2017). "Recently, we reported that NG2-, PDGFRβ-, or αSMA-positive pericytes may be associated with tumor growth in mouse allograft and xenograft models." (PMID 28634350, 2017). "Having confirmed deletion of α6-integrin in pericytes in tumour blood vessels from pdgfrβcre+;α6fl/fl mice in vivo, we asked whether PDGFRβ-driven α6-integrin deletion could affect pericyte association with tumour blood vessels." (PMID 28289267, 2017). "In this present study we support the idea that the significant higher expression of known endothelial markers CD34 and PDGFRB noted on both normal and tumor ADSC could be linked with the potential of ADSC to differentiate into an endothelial-like lineage." (PMID 26968831, 2016).
tumor (continued). "Interestingly, we found that a sub-population of primary human BRAFWT/V600E-PTC cells expressed substantially about 2.5-fold more PDGFRB (tumor microenvironment-associated pro-angiogenic factor) protein vs. PTC cells with BRAFWT." (PMID 26636651, 2015). "Furthermore, vemurafenib therapy significantly (p=0.007) reduced 2-fold vascular density and tumor microenvironment-associated PDGFRB protein levels in the BRAFWT/V600E-KTC1 tumor vs. vehicle-treated mice." (PMID 26636651, 2015). "A possible subgroup that could benefit is patients with estrogen receptor positive tumors undergoing aromatase inhibition therapy, since this treatment has been found to be associated with an upregulation of PDGFRβ on the tumor cells." (PMID 24359404, 2013). "It was suggested that PDGFRB signaling might be implicated in the tumor growth, as imatinib-responding tumors were found to be immunohistochemically positive for PDGFRB." (PMID 22613809, 2011). "PDGFRβ is expressed in a significant higher number of tumor-associated stromal cells than PDGFRα." (PMID 27713269, 2010). "GSEA further revealed that FPR2 is primarily involved in inflammatory and chemokine signaling, while PDGFRB is associated with pathways regulating cell adhesion, migration, and epithelial-mesenchymal transition, underscoring their roles in immune modulation and tumor metastasis." (PMID 41376620, 2025). "Researchers have identified distinct FAP/PDGFRβ dual-positive tumor-associated pericytes in the GBM microenvironment; these cells were demonstrated to be the major FAP-positive cells in GBM and might be CAF-like cells with tumorigenic roles in the GBM microenvironment." (PMID 34068501, 2021). "Notably, lineage tracing also demonstrated that trans-differentiation of PDGFRβ+ pericytes into fibroblasts occurs within a tumor environment, which causes alterations to capillary structure and interstitial matrix components that ultimately enhance tumor invasion and metastatic potential." (PMID 32117997, 2020). "In addition, urinary PDGFRB was significantly positively associated with tumor size." (PMID 24801713, 2014). "As such, the majority of SD/CB in dogs with AGASACA and TC may relate to inhibition of RTKs that are in support of tumor growth (i.e., VEGFR2 and PDGFRβ associated with vascular endothelium and stroma) rather than a direct inhibition of specific RTKs expressed on tumor cells." (PMID 22630170, 2012). "Studies on drugs targeting PDGFRβ have shown that reducing the expression of PDGFRβ in cells can slow down tumor progression." (PMID 41562694, 2026). "Among the 33 metastatic regional lymph nodes examined, nearly half (45.5%) showed PDGFRβ expression in a similar percentage of positive cells as the primary tumor, while another 45.5% had a reduced proportion of positive cells." (PMID 41472102, 2025). "Similar blockable binding was also seen in spleen, which was confirmed to be immunopositive for PDGFRβ, as was the explanted tumor." (PMID 41389114, 2025). "It rapidly reorganizes the tumor’s microvascular architecture by inhibiting targets like VEGFR2 and PDGFRβ, thus mitigating tumor hypoxia and improving the effectiveness of radiotherapy in eliminating hypoxic cells." (PMID 41561735, 2025). "In summary, this study demonstrated that PDGFRβ+ pericytes contributed to ETMR aggressiveness by facilitating stem cell signaling in self-renewing tumor subpopulations, such as RG-like and NProg-like cells." (PMID 40562749, 2025). "To further generalize these findings, we assessed the correlation of AEBP1 expression with CAF markers (ACTA2, FAP, and PDGFRB) and representative collagen family genes across 32 TCGA tumor types." (PMID 41373631, 2025). "Quantitative histoscore analysis revealed 4.7-fold higher PDGFRB expression in tumor vasculature (P<0.001), aligning with CST4’s observed pro-angiogenic effects." (PMID 41040534, 2025).